PON2 (paraoxonase 2)
Diseases named in the same sentence as PON2 in open-access papers (continued):
Sharing a sentence is not in itself a finding about the gene and the disease.
diabetes (10 papers, 2012 to 2024). "Variation in the PON2 gene has been associated with vascular disease, diabetes phenotypes and Amyotrophic Lateral Sclerosis." (PMID 37915799, 2023). "In diabetes mellitus, the PON2-311 SNP associated with the presence of microvascular complications, with an over-representation of the C/C 311 genotype." (PMID 33562328, 2021). "Characteristics of included studies of the association of PON2 Ser311Cys and Arg148Gly genetic polymorphisms with type 2 diabetes mellitus." (PMID 30210454, 2018). "Summary of meta-analysis of association between PON2 Ser311Cys genetic polymorphism and risk of type 2 diabetes mellitus in the Chinese population." (PMID 30210454, 2018). "Summary of meta-analysis of association between PON2 Ser311Cys genetic polymorphism and risk of type 2 diabetes mellitus in the Chinese population after omitting the outliers." (PMID 30210454, 2018). "Summary of meta-analysis of association between PON2 Arg148Gly genetic polymorphism and risk of type 2 diabetes mellitus in the Chinese population." (PMID 30210454, 2018). "A large number of studies have shown that variants of rs12026 within the PON2 gene were associated with cardiovascular disease, cerebrovascular disease, diabetes and other diseases." (PMID 29113331, 2017). "Variants of rs12026 within the PON2 gene were associated with cardiovascular disease, cerebrovascular disease, diabetes and other diseases." (PMID 29113331, 2017). "Lastly, because PPARγ function is important in regulating insulin sensitivity and polymorphisms in PON2 have been associated with diabetes, we evaluated associations with fasting blood glucose levels." (PMID 22860094, 2012). "The importance of the role of PON2 in a variety of aging processes and diseases associated with a high level of ROS has been recently highlighted, including cancer, cardiovascular diseases, neurodegeneration, and diabetes." (PMID 36466095, 2022). "PON1 was also shown to protect from diabetes development in mice, and PON2 was shown to affect hepatic insulin signaling and protected macrophages from high glucose-induced oxidative stress and triglyceride accumulation." (PMID 26779262, 2015). "In macrophages, PON2 has been suggested to protect against the accumulation of triglycerides and oxidative stress, thereby attenuating the development of vascular complications in diabetes." (PMID 33562328, 2021). "Given the importance of ER stress, JNK signaling, and CHOP expression for b-cell homeostasis, PON2 may impact on diabetes." (PMID 33562328, 2021). "Changes in PON-2 have also been shown to influence the development of diabetes." (PMID 31052559, 2019). "The two reported PON2 polymorphisms associate with alterations of plasma lipid levels in patients affected by human diseases related to oxidative stress such as coronary artery disease (CAD), type 2 diabetes mellitus, Alzheimer’s disease, and reduced bone mass in postmenopausal women." (PMID 33562328, 2021). "Quercetin can also improve several pathological conditions such as diabetes and AD through regulation of anti-oxidative stress enzymes via the action of nuclear factor (erythroid-derived 2)-like 2 (Nrf2) and the antioxidant effect of paraoxonase 2 (PON2) expression." (PMID 31195662, 2019).
melanoma (9 papers, 2020 to 2025). A malignant, usually aggressive tumor composed of atypical, neoplastic melanocytes. "PON2’s ability to confer chemoresistance is particularly evident in renal cell carcinoma and melanoma, where its downregulation sensitizes cells to CDDP and 5-FU." (PMID 40794328, 2025). "A correlation has also been observed between PON2 overexpression and poor prognosis in melanoma with heightened cell proliferation and tumour malignancy in the bladder and basal cell carcinomas." (PMID 40794328, 2025). "Enzymes such as N-methyltransferase (NNMT) and paraoxonase-2 (PON2) are also being investigated for their diagnostic and prognostic value in melanoma." (PMID 40941017, 2025). "Melanoma and renal cell carcinoma models similarly show increased oxidative stress upon PON2 knockdown, particularly when combined with chemotherapeutics such as CDDP and 5-FU." (PMID 40794328, 2025). "PON2 gene silencing in melanoma cells has been reported to stimulate ROS production, especially when treated with CDDP." (PMID 40794328, 2025). "Recent studies have firmly established that PON2 is overexpressed in a variety of malignancies, including bladder, gastric, lung, pancreatic, ovarian, and oral cancers, as well as melanoma and leukaemia." (PMID 40794328, 2025). "PON2 expression correlates with important prognostic parameters, indicating its potential as a prognostic biomarker and its involvement in melanoma cell resistance to chemotherapy." (PMID 37629523, 2023). "Paraoxonase-2 (PON2) is another notable biomarker, with significant upregulation observed in melanomas compared to control nevi." (PMID 37629523, 2023). "Another promising therapeutical target in melanoma is the intracellular enzyme, paraoxonase-2 (PON2)." (PMID 37297001, 2023). "The effect of shRNA-mediated PON2 silencing was recently evaluated on viability, proliferation, chemosensitivity and ROS production of A375 melanoma cells." (PMID 36613780, 2022). "It was reported that PON2 expression levels are correlated with tumor aggressiveness of several malignancies, including basal cell carcinoma, squamous cell carcinoma, and melanoma." (PMID 35453297, 2022). "In our recent work, immunohistochemistry was performed to evaluate the expression level of PON2 enzyme in melanoma samples and control nevi." (PMID 33297311, 2020). "To date, this work is the first to analyze the role played by PON2 in melanoma, demonstrating enzyme involvement in those molecular events affecting cell viability and sensitivity to chemotherapeutic drugs." (PMID 33297311, 2020). "The data obtained showed that PON2 was significantly upregulated in melanomas compared to that of controls." (PMID 33297311, 2020). "Data reported in our recent study clearly demonstrated PON2 overexpression in melanoma samples compared with that of control nevi." (PMID 33297311, 2020). "Another enzyme known to be upregulated in melanoma cells is paraoxonase-2 (PON2)." (PMID 40941017, 2025). "A promising enzyme that could serve as a therapeutical target in melanoma is the paraoxonase-2 (PON2)." (PMID 35453297, 2022). "In order to speculate on this hypothesis, in this study, we analyzed the role played by PON2 in melanoma cell metabolism by exploring the effect induced by enzyme knockdown on proliferation, viability, and chemosensitivity of the A375 melanoma cell line." (PMID 33297311, 2020). "Additionally, silencing of the gene responsible for the enzyme in human A375 melanoma cells bearing BRAFV600E mutation has been shown to improve chemosensitivity to cisplatin; thus, paraoxonase-2 inhibitors may be of therapeutic value." (PMID 37297001, 2023). "Although further analyses will be necessary to understand how PON2 could influence melanoma cell metabolism and phenotype, our results seem to suggest that the enzyme may serve as an interesting molecular target for effective melanoma treatment." (PMID 33297311, 2020).
melanoma (continued). "In the light of these results, the evaluation of PON2 as a molecular target for this cutaneous neoplasm deserved to be carried out, focusing on exploring the ability of the enzyme to participate to the mechanisms involved in melanoma cell sensitivity to chemotherapy." (PMID 33297311, 2020). "Although further studies will be necessary to widen our knowledge concerning processes featuring melanoma oncogenesis to which PON2 could participate, our data seem to suggest that the enzyme could serve as a promising molecular target for effective melanoma treatment." (PMID 33297311, 2020). "In addition, enzyme expression was found to be directly related with important prognostic parameters, such as Breslow thickness, Clark level, regression, mitoses, lymph node metastases, pT, and pathological stage, thus suggesting a potential role for PON2 as a biomarker for melanoma aggressiveness." (PMID 33297311, 2020). "The study of NNMT, PON2, Nrf2, MITF, IDO, and MDM2 as potential biomarkers in melanoma holds great promise for improving diagnosis and advancing targeted therapies." (PMID 37629523, 2023). "In this study, we evaluated the impact of paraoxonase-2 (PON2) silencing on proliferation, viability, and resistance to treatment of the A375 melanoma cell line with chemotherapeutic drugs dacarbazine (DTIC) and cisplatin (CDDP)." (PMID 33297311, 2020). "Reported data clearly demonstrate that PON2 is overexpressed in different tumors, including, bladder cancer (BC), ovarian cancer (OC), pancreatic ductal adenocarcinoma (PDAC), gastric cancer (GC) and skin neoplasms, such as basal cell carcinoma (BCC) and melanoma." (PMID 36613780, 2022).
Alzheimer disease (8 papers, 2011 to 2023). A progressive, neurodegenerative disease characterized by loss of function and death of nerve cells in several areas of the brain leading to loss of cognitive function such as memory and language. "Several studies reported the association of PON2 and of codon 311 (S > C) PON2 polymorphism with Alzheimer’s disease (AD)." (PMID 33562328, 2021). "The allele C, of the PON-2 S311C polymorphism, was considered one of the risk factors that can contribute to the development of Alzheimer’s disease in the Chinese population." (PMID 31052559, 2019). "PON2 Cys311Ser polymorphism is also linked with Alzheimer’s disease." (PMID 37891899, 2023). "PON2 C311S polymorphism has been associated with metabolic disorders of cholesterol transport, such as high plasma lipoprotein concentrations, coronary artery disease, complications in diabetes mellitus, ischemic stroke and Alzheimer’s dementia." (PMID 33374313, 2020). "In addition, numerous meta-analyses have been conducted to determine the association of PON2 Ser311Cys and Ala148Gly gene polymorphisms with the risk of developing other diseases, such as coronary heart disease, ischemic stroke and Alzheimer Disease." (PMID 30210454, 2018). "The most common PON2 polymorphisms are associated with its decreased lactonase activity and with a higher risk for coronary artery disease (CAD) and Alzheimer’s disease." (PMID 33562328, 2021).
leukemia (8 papers, 2012 to 2025). A malignant (clonal) hematologic disorder, involving hematopoietic stem cells and characterized by the presence of primitive or atypical myeloid or lymphoid cells in the bone marrow and the blood. "PON2 expression was found to spike in brain and liver malignancies, while leukaemia and glioblastoma display gene loss and amplification, respectively." (PMID 40794328, 2025). "PON2 has been linked to therapy resistance and poor prognosis in different types of leukemia, but the biological function of PON2 in hematopoiesis has not been investigated." (PMID 34257800, 2021). "Lef-1 is part of the Wnt/β-catenin pathway involved in many of the PON2-associated cancers, including leukemias and thus was the most promising candidate from this approach." (PMID 27322774, 2016). "Thus, our studies demonstrate a Wnt/β-catenin-mediated regulation of PON2 expression in leukemias, a finding backed-up by clinical association studies, at least in part." (PMID 27322774, 2016). "Dexamethasone (DEX) sensitivity was found to be increased in leukaemia cell lines through PON2 knockdown." (PMID 40794328, 2025). "Overexpression of PON2 has been shown to inhibit caspase activation and cell death, as observed in leukaemia and endothelial cell models exposed to imatinib or doxorubicin." (PMID 40794328, 2025). "In another study, PON2 knockdown in leukaemia cells increased cell sensitivity to DEX and consequently reduced tumour volume." (PMID 40794328, 2025). "PON2 accelerates chemoresistance in leukemia cells, and silencing PON2 has resulted in spontaneous apoptosis in various human cancer cells." (PMID 28108734, 2017). "The intracellular human enzyme Paraoxonase-2 (PON2) is known to have anti-apoptotic properties in leukemia and oral squamous cell cancer (OSCC) cells." (PMID 27322774, 2016). "Our in vitro results demonstrate, for the first time, an enhancement of PON2 transcription and translation through Wnt/β-cat mediated Lef-1 activation in leukemia and OSCC cells." (PMID 27322774, 2016). "Elevated PON2 levels in K562 leukaemia cells appeared to prevent imatinib-induced cell death." (PMID 40794328, 2025). "PON2 knockdown in the tumor cell lines K562 (leukemia) and A549 (lung cancer) initiated apoptosis, suggesting that PON2 may act as a target for cancer therapy in certain malignancies and fulfill an outstanding function for tumor cell survival." (PMID 28430636, 2017). "Next we asked for contribution of Wnt/β-catenin to PON2 regulation in human malignant neoplasms beyond leukemia, because this type of cancer has been investigated before and for the reason that we wanted to test the more general role of this type of PON2 regulation." (PMID 27322774, 2016). "First, we present a so far unknown regulation of PON2 protein expression through the Wnt/GSK3β/β-catenin pathway in leukemia and OSCC cells." (PMID 27322774, 2016). "Additionally, in various leukemia gene expression profiling studies, upregulation of PON2 could be demonstrated; an example is pediatric acute lymphoblastic leukemia (ALL)." (PMID 33562328, 2021). "Additionally, in various leukemia gene expression profiling studies, an upregulation of PON2 could be demonstrated; an example is pediatric acute lymphoblastic leukemia (ALL)." (PMID 22666600, 2012). "In leukaemia and B-ALL, PON2 deletion via CRISPR-Cas9 attenuates tumour growth and delays cell cycle progression." (PMID 40794328, 2025). "PON2 deletion in two murine B-ALL cell lines markedly compromised their cell proliferation and colony formation ability, and reduced leukemia initiation and development upon transplantation in mice in vivo." (PMID 38397445, 2024). "In another form of leukemia, chronic myeloid leukemia (CML), PON2 was also identified in an outcome-specific gene expression signature of primary imatinib-resistant patients." (PMID 22666600, 2012).
leukemia (continued). "Although PON2 expression has been correlated with the pathology of different forms of leukemia, the role of PON2 in hematopoiesis has not been analyzed." (PMID 34257800, 2021).
glioblastoma (7 papers, 2017 to 2025). The most malignant astrocytic tumor (WHO grade IV). "VPA treatment elevated ROS levels in glioblastoma cells, particularly within PON2-silenced cells, however, PON2 overexpression significantly reduced ROS production." (PMID 40794328, 2025). "In glioblastoma, PON2 modulation by VPA influenced the expression of apoptosis-related proteins such as Bcl-xL, Bim, and p21, while suppressing migration and invasion." (PMID 40794328, 2025). "In glioblastoma-derived cell lines, valproic acid (VPA) causes a dose-dependent downregulation of PON2, which is reversible by 1-benzoyl-3-phenyl-2-thiourea." (PMID 40794328, 2025). "In particular, PON2 expression was shown to be increased in some solid tumors, including pancreatic cancer, glioblastoma multiforme, and recently BC." (PMID 32093309, 2020). "Patients with glioblastoma, low grade glioma, liver hepatocellular carcinoma and acute myeloid leukemia, exhibiting higher expression of PON-2, had poor survival when compared with patients with lower PON-2 expression." (PMID 31052559, 2019). "Although the public database displayed only 4 normal subjects, the average PON2 level in glioblastoma patients was about 2.3-fold that of normal subjects (3.75 vs 1.66)." (PMID 28108734, 2017). "To investigate the downstream signaling pathway involved in PON2-mediated glioblastoma cell growth arrest, we established two transient PON2-transfectants overexpressing PON2 in U87 and GBM8401 cells." (PMID 28108734, 2017). "VPA has also been shown to inhibit glioblastoma growth partly through PON2 suppression." (PMID 40794328, 2025). "PON2 protein expression was found to be increased in glioblastoma multiforme (GBM) compared to normal brain tissue." (PMID 38397445, 2024). "Immunohistochemistry of the PON2 expression level in brain tissue of clinical glioblastoma patients revealed that PON2 expression was increased in GBM cells compared with normal brain cells." (PMID 28108734, 2017). "Through PON2 inhibition, VPA inhibits the growth of glioblastoma growth cells." (PMID 40794328, 2025).
coronary artery disease (6 papers, 2006 to 2025). "The PON2-311 "G" (S allele) has been associated with coronary artery diseases in different populations." (PMID 16551349, 2006). "In the group of female patients with coronary heart disease and in the control group of healthy women genetic variations including the PON1 promoter (-107 C/T, -162 G/A, -831 G/A) and coding region (160 R/G, 192 Q/R,) as well as PON2 311 S/C, and PON3 -133 C/A polymorphisms were evaluated." (PMID 33670025, 2021). "Moreover, a recent meta-analysis in patients with coronary heart disease (CHD) identified a protective association of the Ser311Cys variant, particularly in the overall and Asian populations, reinforcing the clinical relevance of PON2 genetic variation in cardiovascular risk." (PMID 41303537, 2025).
heart failure (6 papers, 2017 to 2024). Inability of the heart to pump blood at an adequate rate to meet tissue metabolic requirements. "The exploration of PON2’s role in cardioprotection reveals its potential in mitigating heart failure, both in experimental models and human contexts, posited to stem from its adeptness in enhancing mitochondrial function and attenuating reactive oxygen species (ROS) generation." (PMID 39411310, 2024). "In contrast, expression levels of paraoxonase enzymes 1-3 (Pon1, Pon2, Pon3), which could detoxify oxidated lipids and alleviate angiotensin-II-induced heart failure, were unaltered in Tg-SCD hearts (Figure A6a–c)." (PMID 34576047, 2021).